IL1B (interleukin 1 beta)
Diseases named in the same sentence as IL1B in open-access papers (continued):
Sharing a sentence is not in itself a finding about the gene and the disease.
breast cancer (continued). "Thus, in many cancers such as breast cancer, cytokines including leptin, IL-1B, IL-6, IL-8, IL-23, IL-17, and IL-10 stimulate while others including IL-2, IL-12, and IFN-γ, inhibit cancer proliferation and/or invasion and enhance the body’s anti-tumor defense." (PMID 36835413, 2023). "However, in human monocytes, the priming step alone is sufficient to mediate CASP1 activation and IL-1β release.Primary and metastatic mammary tumors are promoted by IL-1 signaling." (PMID 37300757, 2023). "Indeed, we find that vehicle-treated ErbB2-induced breast cancer tissue expresses Il1a, Il1b, Il6, and Nfkb1 at a measurable level." (PMID 37098526, 2023). "In the TME, IL-1β is up-regulated in many solid tumors, including breast cancers." (PMID 36835413, 2023). "CCL2 could induce the production of IL-1β in TAMs and lead to neutrophil expansion and systemic inflammation-mediated metastasis in breast cancer." (PMID 36674955, 2023). "In addition, we wanted to determine the cell type responsible for possible IL-1β release and its effects on metastatic breast cancer cells at the early stage of brain colonization." (PMID 37749707, 2023). "When conducting a systematic research review, Salignan’s team proved that increased symptoms of fatigue, especially in women in early stages of breast cancer, were caused by increased concentrations of IL-6 and TNF, and of IL-1β during chemotherapy, and of IL-6 during radiotherapy." (PMID 36834426, 2023). "Moreover, in an inflammatory tumor microenvironment, IL-1β stimulates IL-6 production, which can increase the aggressiveness of luminal-type breast cancer cells." (PMID 37569777, 2023). "By inhibiting IL1B, one may counteract breast cancer’s immunosuppressive effects and boost their anti-PD-1 counterparts, resulting in an anti-tumor impact." (PMID 36969161, 2023). "Breast cancer patients with psychological distress displayed poor cognitive function, poor memory, and inferior quality of life, which was accompanied by higher cytokine levels of IL‐1β, TNF‐α, and IL‐4." (PMID 36965094, 2023). "Finally, IL1B signalling contributed to breast cancer metastasis by enhancing tumor cell motility and inhibiting cell proliferation." (PMID 36497286, 2022). "A previous study showed that soluble CD44 raised the level of IL-1β in breast cancer, and IL-1β could also be activated by soluble CD44 secretion." (PMID 35626430, 2022). "Animal models have shown reduction in breast cancer metastasis with IL-1B inhibition." (PMID 35669467, 2022). "For example, IL-1β regulates the expression of adipocyte-mediated vascular endothelial growth factor A and angiogenesis, which may lead to the progression of breast cancer." (PMID 36147694, 2022). "Thus, similar to our observations in the PDX models, it seems that while most patients exhibit a low to medium expression of CXCL1, CSF2, and IL-1β, a fraction of breast cancer patients exhibit high expression levels of these cytokines." (PMID 36551639, 2022). "Since IL-1β has been described as an inducer of IL-6 expression in colon and breast cancer cells, we reasoned that IL-1β could trigger IL-6 production by Caco-2 cells." (PMID 35326545, 2022). "This present study demonstrated a previously unknown interplay between macrophages and breast cancer cells, regarding M1 macrophages enhancing PIGR expression in breast cancer cells through IL-1β." (PMID 36207349, 2022). "For instance, IL1β expression by tumors cells can support bone colonization in a humanized mouse model of breast cancer, and treatment with either anakinra or canakinumab, both inhibitors of IL1β signaling, significantly reduce the development of experimental bone metastases." (PMID 36561929, 2022). "For example, it is reported that IL-1β induced the expression of COX-2 in breast cancer cells." (PMID 35454744, 2022).
breast cancer (continued). "In parallel, investigations indicated that IL-1β blocking has cooperated with anti-PD-1 treatment in reducing tumor growth in a mouse breast cancer model and that IL-1β could up-regulate PD-L1 expression." (PMID 35884574, 2022). "In addition, in both melanoma and E0771 breast cancer models, IL1β has been shown to increase the anti-tumour potential of T helper (Th1) cells, and genetic knockout of IL1β in mice reduces cytotoxic CD8+ T cells in soft tissue tumours." (PMID 36230739, 2022). "Moreover, although the IL1β inhibitor MLX01 only slightly reduces breast cancer metastasis to the bone, it significantly delays the onset of bone metastasis and reduces tumour growth at the primary site." (PMID 36230739, 2022). "In addition, using a 4T1 breast cancer model, the authors demonstrated that ILC3s are a major source of IL-22 promoted by IL-1β and IL-23." (PMID 36341381, 2022). "Therefore, SRC-3 inhibition suppresses NLR-mediated inflammasome pathways in E0771 tumors by preventing Il-1β function by increasing Il-1ra levels and suppressing breast cancer proliferation." (PMID 36316775, 2022). "Additionally, positive associations between IL-1β, TNF-α and DepS were also found in postoperative breast cancer patients untreated with adjuvant chemotherapy." (PMID 36615742, 2022). "This was also true in another dataset from patients with breast, colorectal, and lung cancer (GSE103512), where mean KRAS/CCL2/IL1B expression was significantly higher in lung and colorectal cancer, which have higher KRAS mutation rates, compared with breast cancer." (PMID 35327394, 2022). "In addition, it has been reported that OSM together with IL-1β induces IL-6 in breast cancer cells in culture, and expression of these three factors correlated with low breast cancer patient survival." (PMID 35163731, 2022). "The function of IL-1β and IL-18 in breast cancer are multiple." (PMID 36119049, 2022). "Interestingly, we found that tumour-derived IL1β decreased the ability of breast cancer cells to invade HUVEC cells (E0771, 0 = 0.0101; Py8119, p = 0.0231), which is opposite to the pro-metastatic effects observed toward the bone metastatic niche." (PMID 36230739, 2022). "Elevated IL-1β correlates with disease severity and poor outcomes in advanced-stage breast cancers." (PMID 35631400, 2022). "The pro-inflammatory cytokine, IL1β, plays a pivotal role in breast cancer bone metastasis." (PMID 36230739, 2022). "Therefore, neutralization of CD44 by antibody decreased IL1β production in macrophages and attenuated the growth of primary breast cancer." (PMID 35464064, 2022). "It was disclosed that IL-1β could enhance the tumor protein 63 (TP63) isoform ΔNP63α, a chemoresistance-associated gene, adding to the cisplatin acquired resistance in breast cancer cells." (PMID 36119049, 2022). "In conclusion, we have documented for the first time that QD3, when used at a relatively low concentration of 1 μM, possessed senolytic activity in etoposide-induced senescent breast cancer cells that was accompanied by decreased pools of p27, IL-1β, IL-8, and HSP70." (PMID 35158873, 2022). "In breast cancer, IL-1β was found to be involved in bone metastasis." (PMID 35626430, 2022). "Furthermore, MDSCs with a polymorphonuclear structure and neutrophils in bone marrow were found to promote DOX resistance in breast cancer through the secretion of IL-1β, which in turn encouraged PI3K/RAC and IL-1RI/β-catenin-dependent BIRC3 transcription." (PMID 36359776, 2022). "Taking our new data together with these studies and previous studies showing near elimination of bone metastasis with Canakinumab and Anakinra, inhibiting IL1β or preventing IL1β binding to its receptor IL1R appears to almost prevent metastatic outgrowth of breast cancer in the bone." (PMID 36230739, 2022). "MCF-7 and MDA-MB-231 breast cancer cells were treated with IL-1β (5, 10, and 20 ng/ml) for 24 h." (PMID 34055597, 2021).
breast cancer (continued). "As many proinflammatory cytokines, including IL-1β, IL-6, and TNF-α, have been strongly linked to breast cancer progression, their suppression could be a key mechanism mediating the chemoprotective role of phytoestrogens in this cancer." (PMID 35008370, 2021). "In another study, cancer patient-derived EVs isolated from peripheral blood samples enhanced expression of vasculature endothelial growth factor A (VEGFA), Wnt5A, and interleukin 1 beta (IL-1β) in human macrophages while significantly enhancing the invasion of breast cancer cells in vitro." (PMID 34656117, 2021). "A similar paracrine signaling mechanism involves GPER-mediated increases in expression of interleukin 1 beta (IL-1β) and IL-1 receptor 1 (IL-1R1) on CAFs and triple-negative breast cancer cells, respectively, resulting in increased migration of breast cancer cells." (PMID 33802978, 2021). "Importantly for breast cancer, aromatase—the rate-limiting enzyme for estrogen biosynthesis—is stimulated in the adipose tissue by adipose-derived factors (IL-1β, IL-6, TNF-α, and prostaglandin (PG) E2) as well as liver-derived IGF-1." (PMID 34066392, 2021). "The hypoxia enhanced the effect of IL-1β in breast cancer cells." (PMID 34055597, 2021). "NLRP3 inflammasome-dependent release of IL-1β induces immune cells, CD4+ T cells, and IL-22 expression and release, which has been associated to initiation and growth of many types of malignancies including breast cancer." (PMID 33840390, 2021). "Disruption of IL-1β–IL-1R signaling by use of a monoclonal IL-1β antibody and an IL-1R antagonist, or by genetic disruption of IL-1R signaling lowered the growth of primary tumor and metastasis to lung and bone in the breast cancer mouse model." (PMID 33686176, 2021). "Notably, depletion of macrophages decreased serum levels of IL-1β, and alleviated breast cancer progression in a syngeneic orthotopic breast cancer mouse model." (PMID 33686176, 2021). "The combined effects of embelin and IL-1β-stimulated hUCMSCs may provide a new therapeutic strategy for breast cancer therapy." (PMID 34282169, 2021). "Both tumour-derived and microenvironment-derived IL-1B promote the infiltration of immune cells that may exert anti-tumour functions, impairing the growth of breast cancer at the primary site." (PMID 34290237, 2021). "Hence, combining IL-1B signalling inhibition with standard of care is a promising treatment for breast cancer bone metastasis." (PMID 34290237, 2021). "Since pharmacological treatments can equally affect the tumour as well as the stroma and previous experiments had used immune-compromised mice, we next addressed the contribution of microenvironment-derived IL-1B on primary tumour growth and immune response to breast cancer in orthotopic models." (PMID 34290237, 2021). "Growth of murine 4T1 mammary tumors mediated by IL-1β was also found in another mouse study." (PMID 34944905, 2021). "In a mouse model of basal-like breast cancer, a complex Notch-dependent paracrine loop between tumor cells and TAMs promoted an immunosuppressive tumor microenvironment, regulating the expression of IL-1β and CCL2." (PMID 33840390, 2021). "Furthermore, analysis of tissue samples from breast cancer patients (stage II/III) revealed that the expression of IL-1β in tumor cells correlated with breast cancer recurrence in bone." (PMID 33809315, 2021). "Thus, FRH inhibits IL-1β and IL-6 mRNA expression in these breast cancer cells in a temperature-dependent manner." (PMID 34201348, 2021). "Besides, macrophage depletion proved to be able to decrease serum IL-1β, and to block breast cancer progression in an orthotopic breast cancer mouse model." (PMID 33840390, 2021). "Furthermore, JUN mediates the functions of some important cytokines in breast cancer, such as IL-34, IL-33, and IL-1β." (PMID 35127514, 2021). "Hypoxic conditions (CoCl2 and 1% O2) enhances the effect of IL-1β in breast cancer cells." (PMID 34055597, 2021).
breast cancer (continued). "Therefore, we then pretreated breast cancer cells with IL-1β, SB203580, and GDC-0941 alone and in combination for Matrigel based cord formation assay." (PMID 34055597, 2021). "Whereas, in breast cancer blocking IL-1 activity with anakinra or the IL-1β specific antibody, canakinumab, reduced breast cancer metastasis by inhibiting epithelial to mesenchymal transition and preventing metastatic outgrowth of disseminated tumour cells via inhibition of wnt signalling pathways." (PMID 35047989, 2021). "Targeting the VM elicited by IL-1β may offer a novel anti-angiogenic therapeutic strategy to control the malignancy of breast cancer cells." (PMID 34055597, 2021). "Moreover, bone marrow-derived IL-1β promoted colonization of breast cancer cells in the bone via induction of nuclear factor (NF)-κB/CREB-WNT signaling in breast cancer cells." (PMID 33686176, 2021). "Moreover, IL-1β secretion stimulated breast cancer colonization as a result of WNT signaling pathway activation and the emergence of an inflammatory microenvironment." (PMID 34452150, 2021). "Inhibiting the IL-1β pathway reduces stepwise metastasis of breast cancer models." (PMID 34055597, 2021). "Breast cancer cell-derived supernatant treated neutrophils significantly expressed high levels of interleukin-1β (IL-1β), CC-chemokine ligand-2-4 (CCL2, CCL3, CCL4), inducible nitric oxide synthase (iNOS), and matrix metallopeptidase-9 (MMP9), and formed extracellular traps (NETs)." (PMID 33049964, 2020). "IL-1β, has also been reported to recruit and activate γ/δ T cells involved in mediating breast cancer metastasis to bone and lung metastasis of melanoma and breast cancer." (PMID 33613533, 2020). "Besides, blockage of this IL-1β pathway inhibits both bone metastasis of breast cancer and CSC colony development in the bone environment." (PMID 33123472, 2020). "Similarly, radiotherapy-resistant breast cancer cells secrete ATP, which in turn associates with its receptor P2Y2R on the cancer cell surface to induce caspase-1 activation and IL-1β release." (PMID 32635472, 2020). "Our findings suggest a mechanism for how IL-22 regulates tumor growth in breast cancer, and indicate blocking IL-22 function might reduce IL-1β- and IL-23-induced tumor progression of breast cancer." (PMID 32649314, 2020). "The induction of EMT in breast cancer by IL-1β also links to an NF-κB-dependent mechanism." (PMID 33123472, 2020). "Soluble CD44 (sCD44) secreted by breast cancer cells induces IL-1β secretion by macrophages, highlighting that the sCD44-1L-1β axis could be considered in IMT." (PMID 32516941, 2020). "In addition to G-CSF, another two pro-inflammatory genes, IL-6 and IL-1β, also exhibited higher expression levels in breast cancer tissue-derived adipose." (PMID 32242230, 2020). "Our findings suggest blocking IL-22 function might reduce IL-1β- and IL-23-induced tumor progression of breast cancer." (PMID 32649314, 2020). "In addition, adipocyte-derived conditioned media induced phosphorylation of AKT and mTOR and upregulated the expression of target genes of the PI3K-AKT-mTOR pathway including IL6, IL1β, IL1α and TNFα in breast cancer cells." (PMID 32201525, 2020). "In breast cancer cells both isoforms were upregulated upon stimulation with IL-1β." (PMID 33042121, 2020). "Breast cancer cell lines that have bone metastasis (MDA-IV) also show an increased expression of IL-1B, which is secreted by both breast cancer cells and osteoblasts, and it has been reported that IL-1B promotes bone metastasis by awakening breast cancer cells that are dormant within the bone." (PMID 32674405, 2020). "Although they did observe tumor progression and spontaneous metastasis in WT mice orthotopically transplanted with 4T1 breast cancer cells, tumors began to grow but regressed and did not form metastasis in IL-1β-deficient recipients." (PMID 32604862, 2020).
breast cancer (continued). "Moreover, it has recently been shown that regression of breast cancer growth in IL-1β KO mice is related, at least in part, to an increase of activated CD8+T lymphocytes." (PMID 33202705, 2020). "Yet, the role of inflammasomes is not limited to IL-1β production and the overall impact of this pathway in the anti-breast cancer response remains unclear." (PMID 33042810, 2020). "Intriguingly, pyroptosis levels of less than 15% were found to be sufficient to clear a complete 4T1 mammary carcinoma graft and this effect depends on circulating IL-1β, as inhibition of IL-1β activity using a specific neutralizing antibody completely nullifies antitumor immunity." (PMID 33584721, 2020). "Finally, macrophage-derived IL-1β was shown to regulate breast carcinoma cell migration and their adhesion to, and transmigration across, blood and lymphatic endothelial cells." (PMID 32635472, 2020). "Notably, genetic ablation of CAF-derived NLRP3 or IL-1β in different syngeneic mouse models delayed mammary tumour growth and/or attenuated lung metastasis." (PMID 31558756, 2019). "It is known that cytokines such as OSM in the stroma of the breast cancer microenvironment play a major role in the progression of metastatic disease, and is possible that IL-1β may also have this type of prometastatic effect." (PMID 31007849, 2019). "The inflammatory signature in primary breast cancers identifies a subset of patients that could potentially benefit from IL-1β-targeted therapies." (PMID 31182982, 2019). "Our data suggest that targeting CAF-derived NLRP3/IL-1β pathway may be a beneficial therapeutic approach for breast cancer treatment." (PMID 31558756, 2019). "IL-1β has been identified as a potential predictor of bone metastasis in breast cancer patients." (PMID 31500658, 2019). "We propose that inhibiting IL1β-NFKB/CREB-Wnt signalling could be an important adjuvant therapeutic strategy in breast cancer to prevent overt bone metastases forming from disseminated tumour cells." (PMID 31676788, 2019). "It was found that IL-1β was able to upregulate the chemoresistance-associated gene, the tumor protein 63 (TP63) isoform ∆NP63α, contributing to the acquisition of cisplatin resistance in breast cancer cells." (PMID 31492049, 2019). "Moreover, trans-endothelial migration of breast cancer cells was attenuated when ECs were incubated with CM of Il1b−/− mammary fibroblasts as compared with CM from WT fibroblasts." (PMID 31558756, 2019). "While there has been a suggestion that IL-1β may also play a role in breast cancer progression, a specific correlation to patient survival has not been previously made." (PMID 31007849, 2019). "In a spontaneous MMTV-PyMT mouse mammary gland tumor model, mature IL-1β levels in primary mammary tumors and metastasis sites were significantly elevated, being associated with inflammasome activation and the infiltration of myeloid cells in tumor microenvironments." (PMID 31182982, 2019). "Knowing that inflammation plays a major role in breast cancer pathogenesis, we sought to elucidate whether OSM and IL-1β work together to promote IL-6 secretion in breast cancer." (PMID 31007849, 2019). "We have previously demonstrated that IL-1B in primary tumours correlates with future relapse in distal organs including bone in breast cancer patients and have now demonstrated that IL-1B is altered between primary tumours and bone metastasis in cell lines and PDXs." (PMID 31783893, 2019). "Furthermore, OSM, IL-6, and IL-1β expression levels in breast cancer tissue are all strongly correlated with each other." (PMID 31007849, 2019). "Among the factors secreted by macrophages, CCL18 was reported to have strong effects on breast cancer progression whereas macrophage-secreted IL-1β, TNF-α, and CCL5 were previously suppressed by IL-32θ; thus, mRNA expression levels of these factors were measured." (PMID 31126309, 2019).